CASC15 (cancer susceptibility 15)
Diseases named in the same sentence as CASC15 in open-access papers (continued):
Sharing a sentence is not in itself a finding about the gene and the disease.
tumor (47 papers, 2016 to 2026). "This downregulated tumor suppressor lncRNA is an isoform of lncRNA Cancer Susceptibility 15 (CASC15) implicated in UM." (PMID 34439196, 2021). "CASC15 acts as a tumour suppressor and is associated with advanced tumour stages and poor patient survival, while NBAT1 seems to negatively regulate transcription factor NRSF (neuron restrictive silencing factor)." (PMID 27233618, 2016). "The negative correlation between VGF and CASC15 suggests a potential antagonistic relationship worth exploring, as CASC15 has been implicated in cancer progression and may affect tumor growth and metastasis." (PMID 40600620, 2025). "Cancer susceptibility candidate 15, termed CASC15, located on chromosome 6p22, was reported to suppress the aggressive tumour progress; and the overexpression of its short isoform (CASC15-S) was found to inhibit neuroblastoma progression and increase patient survival." (PMID 33621953, 2021). "In addition to general transition, CASC15, a tumor suppressor long intergenic noncoding RNA at 6p2234, was disturbed by the chromothripsis-associated rearrangements and gene fusion events involving CASC15 were identified in five UBCs." (PMID 30755618, 2019). "However, the association of CASC15 expression with age, gender and tumor differentiation was unclear." (PMID 29489064, 2018). "CASC15 promotes tumor cell proliferation, migration, and invasion by regulating the expression of multiple oncogenes and tumor suppressor genes." (PMID 40932351, 2026). "Several individual molecular biomarkers—such as circUGP2, lncRNA CASC15, and miR-338-3p—have demonstrated preliminary utility in reflecting tumor biology and predicting patient outcomes." (PMID 41296409, 2025). "CASC15, located on chromosome 6, plays a significant role in cancers biology by promoting tumor cell proliferation, migration, and epithelial-mesenchymal transition (EMT)." (PMID 41286778, 2025). "Another lncRNA that is involved in the maintenance of BCSCs is CASC15, it is overexpressed in the cytoplasm of BCSCs compared to the rest of the tumor cells." (PMID 41181715, 2025). "This was consistent with our finding that, in our results, we clearly observed that CASC15 expression in tumor tissues was notably higher than in paraneoplastic tissues and that CASC15 contributed to the poor progression-free survival of CRC." (PMID 40746360, 2025). "Another study reported that lncRNA cancer susceptibility 15 (CASC15) is upregulated in OS plasma exosomes, and knockdown of CASC15 has been found to impede tumor growth both in vitro and in vivo by targeting the miR-338-3p/RAB14 axis." (PMID 38203737, 2024). "NBAT1’s sense counterpart CASC15 has several isoforms and among which CASC15-003 and CASC15-004 have been shown to display tumor suppressor functions." (PMID 36230680, 2022). "Of note, the isoform CASC15-003 shares common biological pathways with NBAT1 in promoting tumor suppression and inducing neuronal differentiation." (PMID 36230680, 2022). "In osteosarcoma, the circRNA hsa_circ_0005909/miR-338-3p/HMGA1 axis promotes tumor cells proliferation; the CASC15/miR-338-3p/RAB14 axis induces tumor cells growth, migration, and invasion in vitro and in vivo." (PMID 34718336, 2021). "Low expression of CASC15 was closely linked to advanced TNM stage, poorer differentiation, and larger tumour size." (PMID 33834618, 2021). "The bioinformatics analysis showed that the level of CASC15 lncRNA was lower in tumor tissues than that in normal tissues." (PMID 32366932, 2020). "Patients with up‐regulated CASC15 suffered from tumor invasion (P = 0.001), lymph node metastasis (P < 0.001), distant metastasis (P = 0.032) and higher TNM stage (P = 0.049)." (PMID 29489064, 2018). "The tumors derived from the sh‐CASC15‐transfected cell were markedly smaller than that from the control vector‐transfected cell, showing a marked reduction of tumor volume and weight." (PMID 29489064, 2018).
tumor (continued). "In vivo experiments showed that the knockdown of CASC15 lessened the tumor volume and weight and influenced the EMT process." (PMID 29489064, 2018). "GWAS analysis and in vitro assays have demonstrated the tumor suppressor role of CASC15 in NB, but the underlying mechanism has not to be clarified." (PMID 36923440, 2023). "In addition, upregulation of lncRNA CASC15 was observed in HCC, which suggests its positive associations with larger tumor size, higher tumor stage, and early lymph node metastasis." (PMID 35356220, 2022). "Thus, our study utilized bioinformatic analysis to identify the prognostic significance of DR-lncRNAs, including CASC15, LNC00900, AC055720-2, DPH6-DT, and TNRC6C-AS1, which are closely associated with tumor differentiation." (PMID 35267662, 2022). "CASC15 has been reported to be upregulated in various types of tumor tissues, including NSCLC." (PMID 34745939, 2021). "Silencing of CASC15 in NSCLC cells could lead to a remarkable suppression of tumor cell migration and growth." (PMID 33407675, 2021). "Up-regulated expression of lncRNA CASC15 predicts bad prognosis and relates to tumor growth in CC." (PMID 31737900, 2020). "The in vivo experiments showed that the knockdown of CASC15 could impair the tumor volume and weight in nude mice, as well as influencing EMT process, as confirmed by western blot and immunohistochemistry (IHC) assays." (PMID 29489064, 2018). "In addition, highly expressed CASC15 was markedly related to the tumor, node and metastasis (TNM) stage of GC (*P < 0.05, **P < 0.01)." (PMID 29489064, 2018). "The in vivo experiments also demonstrated that the knockdown of CASC15 could weaken tumor volume and weight in nude mice, and influence the EMT process, as confirmed by western blot and IHC assays." (PMID 29489064, 2018). "We identified RCC-specific features including enhanced T cell exhaustion, pro-angiogenic and immunosuppressive MC polarization, and a malignant CASC15+KLK6+ epithelial subpopulation that may drive tumor progression through MIF and CD99-mediated intercellular communication." (PMID 40932351, 2026). "Therefore detecting the expression of CASC15 in tumor tissues is practical." (PMID 31665008, 2019). "For example, CASC15 knockdown inhibits proliferation and migration while inducing apoptosis; PAICC silencing markedly reduces xenograft tumor growth; and FAM66C promotes glycolysis and invasiveness via the miR-23b-3p/KCND2 axis." (PMID 41296409, 2025). "Meanwhile, we noticed that CASC15, CASC8, CASC9, and CASC19 were highly expressed in tumor samples and CASC16 and CASC18 were lowly expressed in tumor tissues." (PMID 40746360, 2025). "In our samples, the expression of KTN1-AS1, CASC15, AC026356.1 and AL606489.1 was higher in tumour tissues than that in paired normal tissues." (PMID 37643369, 2023). "Our preliminary deep sequencing data also showed that CASC15 was upregulated in LSCC and positively correlated with cyclin D1 (data not shown), which mediates cell cycle progression and has critical roles in tumor growth." (PMID 35216636, 2022). "As part of HIF-1α/CASC15/SOX4/β-catenin axis, CASC15 plays an essential role in cell proliferation, invasion, and tumor development in NSCLC." (PMID 34745939, 2021). "Our preliminary deep-sequencing rate revealed that CASC15 was upregulated in TSCC and inversely correlated with miR-214, which has tumor suppressive roles." (PMID 31665008, 2019). "In conclusion, CASC15 was upregulated in TSCC and overexpression of CASC15 may promote TSCC cell migration and invasion by downregulating tumor suppressive miR-124." (PMID 31665008, 2019). "Of these lncRNAs, six were common to tumor cells, RFPL1S (p = 0.019), PPP1R26-AS1 (p = 0.008), RP11-439E19.3 (p = 0.01), CASC15 (p = 5.27 × 10–5), AC004540.5 (p = 0.00042), and CTD-2881E23.2 (p = 8.4 × 10–6), while two were unique to DTCs, ZRANB2-AS2 (p = 0.033) and LINC00511 (p = 0.03)." (PMID 31920530, 2019).
tumor (continued). "Our study first reported that CASC15 was upregulated in TSCC and overexpression of CASC15 may promote TSCC cell migration and invasion by downregulating miR-124, which has tumor suppressive role in TSCC." (PMID 31665008, 2019). "CNV score analysis revealed that Malignant, CASC15+KLK6+EPC, and UBD+S100A11+EPC exhibited significantly higher CNV scores than other subpopulations, indicating that these cells have a higher malignant potential and may play a key role in tumor progression." (PMID 40932351, 2026). "Thus, tumor development and progression in breast cancer may be regulated through axes such as SPRY4-IT1/miR-6882-3p/TCF7L2, LncCCAT1/miR-204/211/TCF4, and CASC15/miR-654-5p/MEF2D." (PMID 41181715, 2025). "To investigate whether CASC15 exerts tumor-promoting effects in NSCLC cells by influencing the expression of neighbouring genes, we firstly performed qPCR to analyze the expression levels of SOX4 and PRL upon CASC15 silencing." (PMID 33407675, 2021). "They reported up-regulation of RFPL1S, PPP1R26-AS1, RP11-439E19.3, CASC15, AC004540.5, and CTD-2881E23.2 while down-regulation of USP3-AS1, CHRM3-AS2 and RP6-99M1.2 in tumor cells compared with the corresponding non-tumor mononuclear cells isolated from bone marrow (MNCs)." (PMID 33718173, 2021). "However, the miR-23b-3p/miR-24-3p-mediated SMAD2 expression decrease occurred only at the translational level, but not the transcriptional level, suggesting that CASC15 utilized another approach to regulate SMAD2 mRNA expression, which also contributed to CASC15's tumor-promoting role." (PMID 35342355, 2022).
cancer (41 papers, 2016 to 2026). A tumor composed of atypical neoplastic, often pleomorphic cells that invade other tissues. "Our study demonstrates that combining MIR4435-2HG with another lncRNA, CASC15 (Cancer Susceptibility Candidate 15), enables the stratification of ESCC patients into distinct molecular subtypes with varying clinical outcomes." (PMID 41286778, 2025). "Based on available human cancer datasets, higher cancer susceptibility candidate 15 (CASC15) expression correlated with the poor prognosis of OC patients." (PMID 38571882, 2024). "This study aimed to explore the level of cancer susceptibility 15 (CASC15) and its effect on inflammatory response in NS." (PMID 34870560, 2021). "Firstly, we identified differentially expressed lncRNA cancer susceptibility candidate 15 (CASC15) as associated with NSCLC based on bioinformatic data." (PMID 33407675, 2021). "Cancer susceptibility candidate 15 (CASC15, OMIM# 616610) is a highly active lncRNA, also known as LINC00340 (Yin, Zhao, Li, & Yin, 2018)." (PMID 32329235, 2020). "Regarding the up-regulated lncRNAs, only a low number of them have been previously implicated in cancer, such as the up-regulated CASC15, LINC00662, LINC01272, LINC00857, LINC00092, LINC00673 and the down-regulated LINC00657, LINC01087 and LINC00993." (PMID 32753692, 2020). "Cancer susceptibility candidate 15 (CASC15) is a highly active lncRNA and involved in the development of cancers." (PMID 32329235, 2020). "The lncRNA CASC15 (cancer susceptibility candidate 15) is a long intergenic non‐coding RNA (lincRNA) locus in chromosome 6p22.3." (PMID 29489064, 2018). "LINC00340, also known as CASC15 (cancer susceptibility 15), is a long, non-coding RNA transcript located on chromosome 6 (6p22.3)." (PMID 30306274, 2018). "Additionally, CASC15 has potential as a diagnostic and prognostic biomarker due to its altered expression in cancer, influencing cancer cell survival and chemotherapy resistance." (PMID 41286778, 2025). "The chromosome 6p22.3 cancer susceptibility candidate 15 (CASC15) locus is frequently amplified in metastatic melanoma tumors and cell lines, and upregulation of CASC15 expression has been associated with metastatic progression to brain metastases in a mouse xenograft model." (PMID 37325482, 2023). "These included a single SNP, rs78466540, near cancer susceptibility candidate 15 (CASC15) gene on chromosome 6 and five SNPs, rs11614480 (lead SNP), rs11615848, rs11614887, rs11615870, rs11615833, in linkage disequilibrium (LD) near RP11-116D17.1 on chromosome 12." (PMID 35409401, 2022). "In this work, we found that one lncRNA, annotated as CASC15 (cancer susceptibility candidate 15) and located in the neighbourhood of the SOX4 locus, could upregulate SOX4 expression in NSCLC cell lines." (PMID 33407675, 2021). "CASC15 presented significant positive correlation with most cancer-related pathways, TGF_BETA_SIGNALING, NOTCH_SIGNALING, WNT_BETA_CATENIN_SIGNALING, ANGIOGENESIS, and PI3K_AKT_MTOR_SIGNALING." (PMID 40746360, 2025). "Studies have found that lncRNA CASC15 can cause β-catenin to enter the nucleus in large quantities through the Wnt pathway, promoting EMT in cancer cells." (PMID 40746360, 2025). "CASC15, an oncogenic factor in tumorigenesis of various cancers including BrC, is known to promote EMT by increasing N-cadherin and vimentin protein levels while decreasing that of E-cadherin via TWIST1." (PMID 40943642, 2025). "LncRNA ZEB2-AS, SOX21-AS1, and CASC15, well-described in human cancer, was highly dysregulated in canine oral melanomas." (PMID 33194754, 2020). "Cancer susceptibility candidate 15 (CASC15) (NCBI GeneID: 401237), also named linc00340, is located on chromosome 6p22.3 and was initially identified as a highly active lncRNA." (PMID 31620370, 2019). "Comparing to adjacent non-cancer tissues, expression of CASC15 was significantly upregulated (p < 0.05), while miR-124 was significantly downregulated (p < 0.05) in TSCC tissues." (PMID 31665008, 2019).
cancer (continued). "Since miR-145 may be related to chemotherapy resistance in a variety of malignant tumors, this was also a potential reason for CASC15 to affect the prognosis of CRC." (PMID 40746360, 2025). "Moreover, although recent studies found that CASC15 not only enhanced cancer cell growth but also stimulated the progress of cancer metastasis via EMT 16, 20, 23, 24, the exact molecular mechanism underlying the oncogenic effect of CASC15 is still unclear." (PMID 35342355, 2022). "In addition, miR-124 overexpression only partially reduced the effects of CASC15 on cancer cell migration and invasion." (PMID 31665008, 2019). "However, to date, little is known about the mechanisms governing CASC15 upregulation in cancer." (PMID 33407675, 2021). "Several differentially expressed lncRNA in fibroid from postmenopausal women have been shown to have oncogenic roles in different types of cancer including HOTTIP, SNHG12, CASC15, ZEB2-AS1." (PMID 40725045, 2025). "LncRNAs, such as LUCAT1, KCNMB2-AS1, CASC15, MIAT, PTOV1-AS2, LINC00680, and RNF217-AS1 were reported to be up-regulated in ESCC and other malignant tumors, validating our RNA-sequencing results." (PMID 35255921, 2022). "Oncogenic lncRNAs in human cancer, including HOTAIR, MALAT1, PCA3, CASC15, and CASC20 are also annotated in dogs." (PMID 33194754, 2020). "CASC15 and miR-124 expression in TSCC tissues and adjacent non-cancer tissues was analyzed by RT-qPCR." (PMID 31665008, 2019). "We found that CASC15 was upregulated, while miR-124 was downregulated in TSCC tissues than in non-cancer tissues of TSCC patients." (PMID 31665008, 2019). "Upregulated CASC15 expression in CRC cells promoted LGR5 expression by inhibiting miR-4310 expression, a state that activates the Wnt/β-catenin signaling pathway in CRC to promote cancer cell metastasis, migration." (PMID 40746360, 2025). "However, CASC15 overexpression resulted in increased migration and invasion rates of TSCC cells, indicating that CASC15 can regulate multiple behaviors of cancer cells." (PMID 31665008, 2019). "Although there have been multiple papers introducing different functions of lncRNA in cancers, information about lncRNA CASC15 in GC is not yet clear." (PMID 29489064, 2018). "In addition, prognostic values of lncRNA CASC15 for cancer have not been evaluated by previous studies." (PMID 31665008, 2019). "Confirming the idea of a positive correlation, RNA-sequencing data from the Cancer Cell line Encyclopedia (CCLE) showed that B-ALL and AML cell lines showed a strong positive correlation between the expression of CASC15 and SOX4, while DLBCL and non-hematopoietic tumor cell lines did not." (PMID 28724437, 2017).
infection (1 paper, 2022). The state of being infected such as from the introduction of a foreign agent such as serum, vaccine, antigenic substance or organism. "Furthermore, after CASC15 specific siRNA transfection or shRNA stable infection, transwell invasion assay showed significantly fewer invaded cells in SKOV3 and ES-2 cells compared with the corresponding control group." (PMID 35342355, 2022).
CASC15 also shares sentences with these, for which no sentence is quoted: acute lymphoblastic leukemia (2 papers); glioma (2); B-acute lymphoblastic leukemia (1); Cognitive impairment (1); Corneal astigmatism (1); intrahepatic cholangiocarcinoma (1); liver cancer (1); metastatic melanoma (1); non-small cell lung carcinoma (1); oral cancers (1); ovarian tumours (1); papillary thyroid cancer (1); renal fibrosis (1); rhabdomyosarcoma (1); serous ovarian carcinoma (1); Type 2 diabetes (1).